CD4 (CD4 molecule)
Diseases named in the same sentence as CD4 in open-access papers (continued):
Sharing a sentence is not in itself a finding about the gene and the disease.
infection (continued). "These individuals show preservation of normal CD4+ T cell counts (>500 cells/μL) despite persistently high levels of viral load (typically more than 10,000 HIV-1 RNA copies/mL) during the chronic phase of the infection." (PMID 39842407, 2025). "The absence of RPMΦ did not impact the CD4+ T cell response during P. yoelii infection, as no notable differences in CD4+ T cell frequencies and activation status were found between WT and KO mice upon infection." (PMID 40746561, 2025). "Finally, we analyzed a CD4+ restricted SARS-CoV-2 specificity (DPB4/S167) (18, –20) and found the ex vivo frequency increased following infection and was maintained for 12 mo (M1: P = 0.0003; M6: P = 0.0029; M12: P = 0.0061)." (PMID 40892914, 2025). "However, post-M.tb H37Rv infection, there is only a trending increase in the magnitude of ID93-stimulated polyfunctional CD4+ TH1 T cells in the lymphocytes isolated from lung homogenates of mice immunized with ID93+EmT4TM." (PMID 40285479, 2025). "Unlike the other mechanisms, DC-SIGN-mediated uptake primarily enables viral capture and subsequent transfer to CD4+ T cells, promoting trans-infection rather than productive replication within DCs." (PMID 41369389, 2025). "Despite this, HIV-1 is capable of exploiting DCs to facilitate viral dissemination, as DCs can capture virions without productive infection, migrate to lymphoid tissues, and transfer virions to CD4+ T cells (8, 9, 12, –, 16)." (PMID 40029073, 2025). "Activated CD4+ T cells are the primary target of HIV infection, and they eventually undergo cell death and release virus particles to further initiate another cycle of infection." (PMID 41012705, 2025). "L'infection VIH avait été diagnostiquée 19 ans plus tôt et il suivait un traitement antirétroviral associant dolutégravir/abacavir/lamivudine (charge virale indétectable, CD4 > 900/μl)." (PMID 40248582, 2025). "To determine how the inhibition of iNOS may further influence the development of an antiviral response in HSV-1 infection, we performed flow cytometry analysis of NK cells, CD4+ T cells, CD8+ T cells in the brain and TGs at 7 days of infection." (PMID 41156686, 2025). "Absence of CXCR6 did not affect the level of infection or CD4+ or virus-specific CD8+ T cell numbers in the brain." (PMID 40581668, 2025). "Compared to previous studies that demonstrated impaired antiviral T cell responses within the brain following neurotropic infection, aged animals in this study demonstrated enhanced infiltration of both CD4+ and CD8+ T cells into the CNS acutely and following recovery from MHV‐A59 infection." (PMID 39550693, 2025). "Therefore, the modulation of CD96 in productively HIV-1–infected CD4+ T cells may provide critical insights into its role in human immunobiology and lever our understanding of its role in T cell signaling and regulation, especially in the context of infection and inflammation." (PMID 40911682, 2025). "This includes: 1) the recruitment of CD4 + PIM into infected fLX, 2) the monocyte nature of iMO and of their dominant antiviral responses, 3) the high enrichment in viral RNA of iMO during infection and 4) the endothelial-mediated myeloid chemotaxis signature at 2 dpi." (PMID 40920821, 2025). "To test this hypothesis, we knocked out CPSF5 in primary CD4+ T cells using 2 independent guide RNA in 3 independent donors and conducted HIV-1 spreading infection assays as before alongside NT, CXCR4 knock-out, and CYPA knock-out controls." (PMID 41385587, 2025). "After secondary infection, total TCRβ+ T cells and CD4 + T cells were not significantly different between C. auris and C. albicans infected groups." (PMID 40294061, 2025). "Importantly, in vitro‐generated CD4 TIA cells are functional in vivo, and produce IFN‐γ in an antigen‐independent manner during the innate stages of an unrelated infection." (PMID 40923840, 2025). "In the acute phase of infection, α4β7high/CCR5+ CD4+ T cells are preferentially infected." (PMID 40747422, 2025).
infection (continued). "Around half of CD4 T cells expressed both CD69 and CXCR6 beyond 4 weeks post infection." (PMID 40060443, 2025). "Besides serving as viral reservoirs, HTLV-1-infected CD4+ and CD8+ T cells can produce both pro- and anti-inflammatory cytokines during infection progression." (PMID 41150766, 2025). "Initial infection leads to viral integration into host CD4+ T-cells and approximately 5% of cases lead to a highly aggressive subtype of T-cell lymphoma, adult T-cell leukemia/lymphoma (ATL), often occurring decades after the initial infection." (PMID 40573426, 2025). "In addition, our studies identified elevated CD4+ T cells that express Ifng and perpetuate the activation of macrophages within the joint tissue of CHIKV-infected mice at late times post-infection." (PMID 40678223, 2025). "All patients with a single CD4+ determination < 200 presented infection during follow-up, none of which was serious." (PMID 41439928, 2025). "Importantly, spreading infections, initiated with equivalent low multiplicities of infection, revealed ExoI helps to restrict infection of the CEM.SS CD4+ T-cell line." (PMID 39205287, 2024). "Newborn and infant rhesus macaques also have greater counts and frequencies of CD4+ T cells, notably activated CD4+CCR5+ memory T cells that are prime targets for infection with SIV and may be a key target cell population during vertical HIV acquisition." (PMID 39190496, 2024). "Although CD4+T cells have a central role in coordination of the host defenses against fungi, the cytotoxic effect of CD8+T-cells seems ultimately to be essential for termination of the infection." (PMID 39726780, 2024). "Although cells of the myeloid lineages, including tissue macrophages and conventional dendritic cells, were rapidly recognized, in addition to CD4+ T lymphocytes, as target cells of HIV-1, their specific roles in the pathophysiology of infection were initially largely neglected." (PMID 38400063, 2024). "Indeed, a recent report highlighted that during infection with SFB, IEC expression of MHC-II was required for CD4+ T cells to promote IEC turnover." (PMID 38718306, 2024). "It was observed that GITR expression decreased in CD8 Tregs, but not in CD4 Tregs, in patients with undetectable vs. those with detectable HbsAg levels 6 months post-infection." (PMID 39061246, 2024). "Cell fusions of syncytia formation are more possible for the CD4+ T-cells upon infection by the CXCR4-tropic HIV strains but not for cells that do not support productive infection of the replicating virus particles, such as the stem-progenitor cells." (PMID 39810915, 2024). "Furthermore, infection with AD234, a virulent FAdV-4 strain, decreased the number of CD3-, CD4-, and CD8-positive T cells in the spleen, as well as the number of CD4- and CD8-positive T lymphocytes in the thymus." (PMID 38915924, 2024). "This was accompanied by increased IFN-γ-producing CD4+ and CD8+ T-Cells at 8-days post-infection." (PMID 39877362, 2024). "The frequencies of Ki67+CD4+ and Ki67+CD8+ populations were also highly increased after D1MT treatment relative to other groups, although the effect was not statistically significant due to heterogeneity in data obtained from the low-dose infection model." (PMID 39114981, 2024). "While these initial results were promising, there was no evident progressive CD4+ T-cell depletion or disease progression following infection with these first-generation stHIV-1 chimeras." (PMID 39459950, 2024). "The infection occurs through CD4, although not typically found in the NK lineage, can be upregulated in NK cells upon infection with human herpesvirus 6 (HHV-6)." (PMID 38216935, 2024). "Taken together, these data indicate that SHIVAD8-EO infection followed by early bNAb treatment affected the dynamics of CD4+ T cells but not of other immune cell subsets in either peripheral blood or LNs." (PMID 39198422, 2024).
infection (continued). "Flow cytometry analysis revealed that CD4+, CD8+, and γδ+ T cell subsets all contributed to both IL-17 and IL-22 production on day 3 after infection, and the inhibition of IL-10 significantly enhanced the production of these cytokines by all T cell subsets." (PMID 38973612, 2024). "People with HIV who have detectable HIV viral loads at any time are at increased risk of active TB by reactivation of latent TB, reinfection, or rapid progression after recent infection, regardless of their CD4 cell counts." (PMID 39453919, 2024). "This study indicates that the inhibitory receptor-mediated regulation of CD4+ T cells is not correlated with the outcome of infection in early HCV infection, and persistent HCV viremia leads to a sustained upregulation of PD-1 and CTLA-4." (PMID 38668286, 2024). "Of note, at day 21 pi CD4+ depleted mice show high titer viremia, while non-depleted mice have mostly cleared the infection." (PMID 39392861, 2024). "Polyfunctional CD4+ and CD8+ T cells were detected following infection by both routes." (PMID 38621405, 2024). "TGF-β levels in liver-tissue did not increase during infection and were not affected by a lack of CD4+ T cells." (PMID 39392861, 2024). "Sheep were depleted of CD4+ (n = 7), CD8+ (n = 7), or WC1+ γδ (n = 7) T cells by intravenous administration of specific mAbs (GC1a, CC63, and CC15, respectively) over five consecutive days, initiated 2 days prior to infection with BTV (BTV-4 MOR2009/07)." (PMID 38357545, 2024). "During acute HIV infection (10 days post-infection), all mice treated with IFNs showed no signs of CD4+ T cell depletion, while untreated HIV-infected controls exhibited complete CD4+ T cell depletion." (PMID 38543729, 2024). "However, the percentage of IL-22+ CD4+ T cells and IL-22+ ILC3 was maintained at an equal level in the water-restricted mice compared to the control group on days 12 post-infection." (PMID 38799550, 2024). "CD4+ T cells were increased in the lungs on day 4 post RSV infection but were not significantly altered by LPS exposure before infection." (PMID 39127259, 2024). "For B. pertussis, the CD4+IL-17+ T cells generated during natural infection are essential for reducing bacterial colonization of the nose." (PMID 39267766, 2024). "Monkeypox virus neutralizing antibodies were found to be associated with the previous smallpox vaccination status (p: 0.03) and to be living with HIV (p: 0.04), but not with the CD4+ T lymphocyte levels at the time of mpox infection diagnosis (p: 0.80)." (PMID 38793563, 2024). "SW114 (waaI), SW116 (waaJ), and SW118 (waaL) were capable of conferring significant protection against infection of wild-type S. Enteritidis and S. Choleraesuis, with SW118 (waaL) triggering significant CD4+ T-cell responses as well as the B220low IgG+ BM cell." (PMID 39529227, 2024). "Neither CD4+ nor CD8+ T-cell-depleted mice exhibited any significant histological changes in the lungs or spleen after infection or signs of disease, which underscores the role of T cells in LASV pathogenesis." (PMID 39256346, 2024). "This small molecule exhibits new and unique anti-HIV-1 properties, blocking infection both in Rev-dependent indicator T cells and human primary resting CD4+ T cells without detectable cytotoxic effects." (PMID 39146384, 2024). "Taken together, these data clearly show that late-rising M09 CD4 T cells, which differ from other conventional MCMV CD4 T cells that expand early during infection, play a key and non-redundant role in resolving persistent viral replication in the SG." (PMID 38236791, 2024). "In contrast, no significant changes were observed for the expression of IL27p28 and EBI3 mRNA in the animals, irrespective of CD4 count or infection status." (PMID 38966644, 2024). "There was no discernible change in total CD4 T cells or any CD69+ cell populations over the course of infection." (PMID 39150988, 2024).
infection (continued). "The blockade of TIM-3 signaling in spleen lymphocytes from S. japonicum infected mice by treatment with soluble TIM-3-Fc fusion protein increased the population of CD4+IFNG+ Th1 cells, suggesting that TIM-3 signaling suppresses Th1 cell activity during infection." (PMID 38979184, 2024). "We also showed that the absence of CD4+ T cells throughout acute NrHV infection (depletion prior to infection) leads to long-term viral chronicity, establishing an essential role for these cells in providing protective immunity." (PMID 39392861, 2024). "During early infection, R5 T-cell tropic viruses, characterized by their ability to efficiently enter CD4+ T-cells but not macrophages and microglia, represent the majority of the viral population." (PMID 38713307, 2024). "The route of administration for mucosal BCG vaccination and Mtb challenge in RMs was similar, but only Mtb increased frequencies of HLA-E–Mtb CD4+ and CD8+ T cells, suggesting that differences in the infection cycle or virulence influenced the capacity to induce HLA-E–Mtb-restricted T cells." (PMID 39460296, 2024). "Viruses circulating during untreated infection are almost exclusively well-adapted to infection of CD4+ T cells and not macrophages (i.e. are T cell-tropic, requiring a high density of CD4 for efficient entry)." (PMID 38422171, 2024). "Of note, in our in vitro model, more than 95% of CD4+ T cells differentiated into an effector-memory phenotype based on CD28loCD95hi expression by day 4 after infection and day 7 after activation, respectively (data not shown)." (PMID 38557496, 2024). "When HIV-1 chimeric viruses were generated, expressing a functional or non-functional Vpx protein instead of the HIV-1 Vpr protein, productive infection of the CD4+ T cell line Sup-T1 was obtained only in the absence of Vpx expression." (PMID 38787201, 2024). "The level of CD4 + T cell and CD8 + T cell, and NK cell counts at six months are similar to our results, and we complemented the change of immune cells at 1 week and 3 months after infection." (PMID 38844850, 2024). "(2014) described a composite “immunological score” using immunoglobulins (IgG, IgM, IgA), complements (C3, C4), and lymphocyte subsets (CD3+, CD4+, CD8+ T cells, NK cells, and B-cells) correlating with severe infections in a cohort of heart transplant recipients." (PMID 39660122, 2024). "Decreased CD4+/CD8 + ratio and increased NK cells were seen after infection." (PMID 38678181, 2024). "This discordance across the tissues suggests that increased CD4+ T cells infection frequency in the EM is not explained by observed increases in CCR5 expression following menopause." (PMID 39872519, 2024). "Therefore, we examined pSOTR and pHC responses to both vaccination and vaccination plus infection by analyzing total anti-SARS-CoV-2 IgG titers, surrogate neutralization capacity, and cytokine production and proliferation of S-specific CD4+ and CD8+ T cells." (PMID 38580714, 2024). "In contrast, individuals who have resolved the infection (tested HCV RNA negative) have stable levels of virus-specific CD4+ T lymphocytes, even 100 days after infection." (PMID 38690280, 2024). "Strong, broad, specific, vigorous, and multispecific CD4+ T helper cells and CD8+ cytotoxic T cell responses targeting the non-structural protein of HCV have been detected during the early stage of the infection in people who spontaneously resolve infection." (PMID 39205311, 2024). "Analysis of T cell subsets in people with Sh infection compared to individuals without infection showed lower CD4+ (257 versus 681) and higher CD8+ (210 versus 114) T cells/μL in a Nigerian cohort without HIV infection." (PMID 39250522, 2024). "The immune response of the host activates CD4+ and CD8+ T cells to control the infection." (PMID 37368949, 2024).
infection (continued). "Similarly, after infection with Listeria monocytogenes, TNFR2 signaling enhanced the survival and clonal expansion of CD4+ and CD8+ T cells, thereby promoting pathogen elimination and neuroprotection." (PMID 38339126, 2024). "Although CD4+ and CD8+ glycophenotypes are different and are modified during acute T. gondii infection, SN was the only lectin whose binding revealed a novel T cell population that lost Sial α2,6 due to infection." (PMID 39253089, 2024). "Only combined CD4 and CD8 depletion led to an increased frequency of M. tuberculosis-infected neutrophils, suggesting that CD4 and CD8 T cells are redundant in their ability to control infection in these cells." (PMID 38977711, 2024). "At 7 weeks post bone marrow transplant from wild type donors, WHIM recipient mice had similar numbers of circulating white blood cells, including neutrophils, monocytes, CD4 and CD8 T cells, and B cells at both pre-infection and 4 weeks post infection time points compared to wild type recipients." (PMID 39226327, 2024). "In another study, the iv adoptive transfer of lung CD4+ T cells into naïve C57BL/6 mice prior to challenge resulted in a significant reduction in the bacterial load in the lungs and spleen 24 h post-infection with a mucoid hypervirulent K. pneumoniae KP-396 strain." (PMID 39408879, 2024). "In line, using the standard centrifugation protocol, the studies performed here revealed stronger responses of CD4+ T cells from patent mice than those observed in cultures from Mf-negative mice at the same stage of infection (day 72 p.i.)." (PMID 39436444, 2024). "In addition to the direct killing of some CD4+T cells by HIV, early HIV regulatory proteins Nef and Tat are released during the acute phase of infection." (PMID 38504106, 2024). "NKT cells may be restored with the initiation of ART, but CD4− NKT subpopulations return more robustly than CD4+ NKT subpopulations, and overall NKT numbers are lower than physiological infection-free levels." (PMID 39609320, 2024). "Thus, in addition to viral genomic RNA concentrations, anti-spike IgG titers, and virus-specific CD4+ and CD8+ concentrations, we included the dynamics of these three genes in our mathematical model of infection." (PMID 39575237, 2024). "Furthermore, we conducted an analysis of the CD8+/CD4+ ratio, cytokine secretion, T cell phenotype and expression levels of exhaustion markers to assess the effects of HSV-1dko-GFP infection." (PMID 38953982, 2024). "Six months after chemotherapy, the Th1:Th2 ratio increased and MTB specific IFN-γ and TNF-α producing CD4+ T cells were detected, but all of these remained lower than in children without Sh infection." (PMID 39250522, 2024). "As largely exemplified in early studies performed on post-mortem material, it is generally admitted that CD4+ T cells do not directly contribute to infection of the CNS." (PMID 38400063, 2024). "In case of homologous vaccination with two doses (AZ/AZ and PZ/PZ), median T-cell response values were negative except CD4+ response in individuals vaccinated with double dose and previous infection." (PMID 38572317, 2024). "HIV transcription was detectable only in a small number of CD4+ T cells—less than 0.000016% or 16.4 per million cells—of people with HIV with viral suppression on ART, whereas another study suggested an infection frequency of 0.01–0.001%." (PMID 39060113, 2024). "Both CD4+ and CD 8+ T cells were critical to clear the SARS-CoV-2 during primary infection in mice." (PMID 38299865, 2024). "In contrast, the reactivity to MST in LCL caused by L. (L.)amazonensis is weak or negative and completely regresses as the infection progresses to the hypoergic pole (CD4+/Th2 type) of the ACL spectrum represented by severe and incurable ADCL." (PMID 39334233, 2024). "IFN-I-induced TRAIL expression on pDCs license them to kill CD4 T cells irrespective of their infection status." (PMID 38777879, 2024).